NXF2B (nuclear RNA export factor 2B)
Description:
Involved in the export of mRNA from the nucleus to the cytoplasm.
Synonyms: bA353J17.1
Gene: Protein-coding gene on chromosome X (102,360,395 to 102,440,008, reverse strand). Ensembl gene ENSG00000269437.
Subcellular location: Nucleus, nucleoplasm; Cytoplasm
Pathways (Reactome):
Metabolism of RNA: Transport of Mature mRNA derived from an Intron-Containing Transcript
Gene Ontology:
Molecular function: protein binding; RNA binding; nucleic acid binding
Biological process: mRNA export from nucleus; poly(A)+ mRNA export from nucleus; RNA transport; mRNA transport
Cellular component: nuclear RNA export factor complex; cytoplasm; cytosol; nucleoplasm; nucleus
Homologues: Orthologues: rat Nxf7 (56% identical), mouse Nxf7 (54% identical), rat Nxf2 (53% identical), mouse Nxf2 (52% identical), zebrafish nxf1b (46% identical), tropical clawed frog nxf1 (45% identical), zebrafish nxf1a (39% identical), Caenorhabditis elegans nxf-1 (25% identical), Caenorhabditis elegans nxf-2 (17% identical), Drosophila melanogaster nxf4 (13% identical). Paralogues in human: NXF2 (100% identical), NXF1 (58% identical), NXF3 (46% identical).
Diseases named in the same sentence as NXF2B in open-access papers:
NXF2B is named in the same sentence as 2 diseases in open-access papers, as found by Europe PMC text mining. Sharing a sentence is not in itself a finding about the gene and the disease. The quoted sentences say what the papers report.
pan (1 paper, 2023). "In pan cancer, NXF2B, MSLNL, PCGF1, INO80B-WBP1, LBX2-AS1, MRPL53, LBX2, TTC31, WDR54 and WBP1 were co-altered in the TLX2-altered group." (PMID 37758722, 2023).
NXF2B also shares sentences with these, for which no sentence is quoted: cancer (1 paper).